SF1 (splicing factor 1)
Description:
Necessary for the ATP-dependent first step of spliceosome assembly. Binds to the intron branch point sequence (BPS) 5'-UACUAAC-3' of the pre-mRNA. May act as transcription repressor.
Synonyms: BBP; mBBP; ZFM1; ZNF162; ZCCHC25; D11S636
Tractability: Small molecule: a structure with a bound ligand is known. PROTAC: ubiquitination databases record sites on it; its protein half-life has been measured.
Gene: Protein-coding gene on chromosome 11 (64,764,606 to 64,778,786, reverse strand). Ensembl gene ENSG00000168066.
Subcellular location: Nucleus
Subcellular location (Human Protein Atlas): Nucleoplasm
Pathways (Reactome):
Metabolism of RNA: mRNA Splicing - Major Pathway
Gene Ontology:
Molecular function: identical protein binding; protein binding; RNA binding; transcription corepressor activity; nucleic acid binding; zinc ion binding
Biological process: mRNA 3'-splice site recognition; mRNA cis splicing, via spliceosome; mRNA splicing, via spliceosome; spliceosomal complex assembly; negative regulation of DNA-templated transcription; negative regulation of smooth muscle cell proliferation
Cellular component: nucleoplasm; spliceosomal complex; U2AF complex; nucleus; ribosome; nuclear body
Genetic constraint (gnomAD): Loss-of-function variants: 7 observed, 59.79 expected, observed/expected ratio (o/e) 0.12, 90% interval 0.066 to 0.22. The synonymous counts are far from expectation, so gnomAD's model fits this gene poorly and the ratio says little. Missense variants: 578 observed, 861.48 expected, observed/expected ratio (o/e) 0.67, 90% interval 0.63 to 0.72. Synonymous variants: 394 observed, 316.39 expected, observed/expected ratio (o/e) 1.25, 90% interval 1.15 to 1.35.
Homologues: Orthologues: dog SF1 (100% identical), macaque SF1 (100% identical), pig SF1 (99% identical), rat Sf1 (98% identical), mouse Sf1 (94% identical), rabbit SF1 (93% identical), guinea pig SF1 (89% identical), chimpanzee SF1 (83% identical), zebrafish sf1 (78% identical), tropical clawed frog sf1 (72% identical), Drosophila melanogaster SF1 (43% identical), Caenorhabditis elegans sfa-1 (36% identical). Paralogues in human: QKI (17% identical), KHDRBS2 (15% identical), KHDRBS1 (15% identical), KHDRBS3 (14% identical).
Diseases named in the same sentence as SF1 in open-access papers:
SF1 is named in the same sentence as 143 diseases in open-access papers, as found by Europe PMC text mining. Sharing a sentence is not in itself a finding about the gene and the disease. The quoted sentences say what the papers report.
Obesity (24 papers, 2007 to 2025). Accumulation of substantial excess body fat. "Further research is needed to identify the possible sex hormone related or independent pathways linking NR5A1/SF-1 to obesity risk." (PMID 39479520, 2024). "The observed association of deleterious NR5A1/SF-1 variants with obesity supports the proposed involvement of SF-1 in regulating energy metabolism, beyond its role in reproductive function." (PMID 39479520, 2024). "Despite these limitations, our study proposes links between rare predicted deleterious missense NR5A1/SF-1 variants with obesity and adverse metabolic outcomes." (PMID 39479520, 2024). "There is limited previous evidence on the possible link between rare NR5A1/SF-1 variants and obesity in humans." (PMID 39479520, 2024). "Here, we report that deletion of SF-1 in the VMH leads to late onset of obesity that is largely associated with increased food intake, blunted energy expenditure and reduced physical activity in the aged KO mice." (PMID 27598259, 2016). "Specifically, loss of leptin signaling in SF-1 neurons in the VMH resulted in diet induced obesity due to impaired energy expenditure and increased food consumption." (PMID 27598259, 2016). "Observations from the Sf-1 KO mice models suggest that loss of SF-1 is associated with impaired energy balance and low temperature expenditure leading to late-onset type of obesity." (PMID 25122490, 2014). "In our study the association of rare NR5A1/SF-1 variants with obesity particularly in women, could be linked to sex-specific hormonal dysregulation, potentially rendering women with these variants more susceptible to obesity compared to men." (PMID 39479520, 2024). "Our study not only emphasizes the genetic association between rare predicted deleterious NR5A1/SF-1 variants and obesity but also underscores the need for more comprehensive research to bridge the translational gap between mouse models and humans, younger and older age, as well as sex differences." (PMID 39479520, 2024). "Interestingly, a similar phenotype was observed in humans with mutations of the SF1 gene, who often show mild to severe obesity." (PMID 34201257, 2021). "Similarly, the VMH has been identified as a key reaction site for leptin, VMH specific SF-1 knockout mice display leptin resistance and are susceptible to diet-induced obesity." (PMID 33071984, 2020). "Whereas whole body SF-1 knockout is lethal due to adrenal insufficiency, corticosterone injection and adrenal transplants rescues the SF-1 knockout mice but is accompanied by severe obesity indicating that SF-1 deficiency alters energy metabolism." (PMID 27598259, 2016). "In addition, reduced expression of BDNF was described in association with obesity in the leptin receptor deficient mouse, the Alzheimer disease mouse and the Sf-1 KO mouse." (PMID 25122490, 2014). "Through further protein domain association testing, we identified that women who carry rare deleterious missense NR5A1/SF-1 variants located in the DBD and LBD also have an elevated risk of obesity." (PMID 39479520, 2024). "While numerous studies in mouse models establish the role of SF-1 in metabolic regulation, limited data are available for DSD individuals with rare deleterious NR5A1/SF-1 variants and their association to obesity or overweight." (PMID 39479520, 2024). "Subsequent investigations into the impact of SF-1 on leptin signaling and the development of obesity, especially under high-fat diet conditions, further informed on the multifaceted role of SF-1 in metabolic adaptation." (PMID 39479520, 2024). "SF-1 can directly impact the VMN development such that the deletion of SF-1 or leptin receptor in SF-1 neurons leads to obesity in mice." (PMID 35721722, 2022). "A particularly powerful strategy developed for the exploration of SF1 neurons in obesity and diabetes has been the design of the SF1 Cre mice." (PMID 34201257, 2021).
Obesity (continued). "Prompted by the increased food intake and late onset of obesity in the KO mice, we wondered about the effect of SF-1 in the VMH on energy expenditure." (PMID 27598259, 2016). "The VMH-specific SF-1 knockout mice (KO) exhibited late onset of obesity characterized by hyperphagia, hyperinsulinemia, hyperleptinemia and a marked reduction in energy expenditure and physical activity." (PMID 27598259, 2016). "We previously reported that postnatal deletion of SF-1 in the VMH leads to high fat diet induced obesity due to impaired thermogenesis and blunted leptin signaling." (PMID 27598259, 2016). "In the present study, we found that chow-fed SF1-p110α-KO males showed normal body weight balance, whereas female mutant mice developed obesity." (PMID 26988598, 2016). "Mice with a VMH-specific SF-1 knockout show high-fat diet-induced obesity due to impaired thermogenesis and reduced energy expenditure." (PMID 26750456, 2016). "Central effects could be mediated via SF-1 neurones in the ventromedial hypothalamus, where selective insulin receptor knockout also induces resistance to high fat diet-induced obesity." (PMID 40152560, 2025). "In contrast, obesity could be induced by ablating Rai1 from Sim1-lineage neurons and, to a lesser extent, SF1-lineage neurons." (PMID 37956053, 2023). "Indeed, the knockout of either SF-1 or any one of several components of the melanocortin system (e.g., β-endorphin, melanocortin-4 receptors) leads to hyperphagia, obesity, hyperleptinemia and hyperinsulinemia." (PMID 29973869, 2018). "In addition, this metabolic disturbance at a young age was exacerbated when the KO mice were exposed to high fat diet indicating the important role played by SF-1 in protection against diet and age induced obesity development." (PMID 27598259, 2016). "Although we did not measure the plasma norepinephrine levels in the current study, to partly assess the SNS activity, we expect that deletion of SF-1 in the VMH is likely to be associated with decreased norepinephrine levels as shown by the diminished BAT activity and the late-onset obesity." (PMID 27598259, 2016). "Having observed significant insulin and leptin resistance in young SF-1 KO mice, we speculated that hormonal dysregulation might already have occurred at a younger age before the development of obesity in aged KO mice." (PMID 27598259, 2016). "Obesity might be mediated through Sf-1 regulating activity of brain-derived neurotrophic factor (BDNF), an important regulator of energy balance in the ventromedial hypothalamus." (PMID 25122490, 2014). "Since a large number of studies indicate that induction of thermogenesis may be useful to treat obesity and eventually obesity-related disease, SF-1 neurons are a potential target for development of anti-obesity drugs." (PMID 23675313, 2013). "Our observation that inhibiting CerS6-dependent ceramide synthesis in SF-1 and POMC neurons improves glucose homeostasis during HFD feeding, particularly in male mice, underscores the critical role of CerS6-derived ceramides in obesity-associated ER stress in these types of neurons." (PMID 38016943, 2023). "Thus in our small cohort of rather young patients with heterozygote SF-1 mutations overweight or obesity seems not an issue." (PMID 25122490, 2014). "In addition, the Sf-1 knockout mouse develops obesity with age." (PMID 25122490, 2014). "Furthermore, the effects of SF-1 in tumorigenesis and in other physiological systems (e.g. appetite regulation, obesity, anxiety) might be important if data from mouse studies are extrapolated into humans." (PMID 21078366, 2011). "Indeed, SF1 gene knockout mice displayed an abnormal VMH development leading to obesity." (PMID 20976162, 2010). "Third, ablation of AMPKα1 in SF-1 neurons mimics the actions of T3 in the VMH by enhancing BAT thermogenesis and WAT browning, which in turn protects mice from diet-induced obesity." (PMID 33071984, 2020).
Obesity (continued). "Since hormones like E2 act through PI3K/Akt to diminish EC tone at VMN SF-1/ARC POMC synapses, it stands to reason that decreased ARC PI3K/Akt signaling observed with diet-induced obesity/insulin resistance in males would do just the opposite." (PMID 29973869, 2018). "In the current study, SF-1 deletion in the VMH also induced hyperphagia, hormonal dysregulation and subsequent obesity development." (PMID 27598259, 2016). "Deletion of SF-1 in the VMH resulted in dysregulated insulin and leptin homeostasis and late onset obesity due to increased food intake under normal chow and high fat diet conditions." (PMID 27598259, 2016). "In the presented study, we tried to establish the role of SF-1 in the regulation of human BDNF, an important player for central energy balance and thus obesity." (PMID 25122490, 2014). "Selective deletion of Sf-1 in the VMH in mice prenatally resulted in late onset obesity, while the same deletion postnatally led to diet induced obesity and deregulated thermogenesis." (PMID 25122490, 2014). "The knockdown of Bdnf in SF1 neurons, which must be regarded as non-specific, since Sf1 is expressed in at least three distinct neuronal clusters, promoted hyperphagia and obesity." (PMID 41219904, 2025). "SF-1 KO mice exhibited late-onset obesity due to decreased energy expenditure rather than hyperphagia, establishing them as potential model for hypothalamic late-onset obesity." (PMID 39479520, 2024). "Further, clinical analysis on the expression pattern of FoxO1 and SF-1 in patients with obesity and type 2 diabetes could shed more light on the relationship between HPA axis dysregulation and obesity development." (PMID 29567944, 2018). "With diet-induced obesity/insulin resistance brought on by long-term exposure to a HFD in males, the ability of these neurons to execute their functions becomes impaired, perhaps through augmented EC signaling at VMN SF-1/ARC POMC synapses." (PMID 29973869, 2018). "Mice lacking leptin receptor in SF-1 expressing neurons specifically in the VMH exhibited metabolic syndrome features including obesity, elevated insulin and leptin levels and impaired glucose tolerance." (PMID 27598259, 2016). "Similarly, disruption of the PI3K catalytic subunit, p110α, and postnatal deletion of SF-1 in the VMH also resulted in reduced energy expenditure and development of high-fat diet-induced obesity." (PMID 27598259, 2016). "Notably, 32.3% of women who carried rare deleterious missense NR5A1/SF-1 variants located in the DBD and LBD had obesity, compared to 23% of noncarriers." (PMID 39479520, 2024). "Interestingly, although BDNF is required in the VMH and DMH to regulate body weight, embryonic deletion of Bdnf from the SF1-lineage populations including the VMH did not result in obesity." (PMID 37956053, 2023). "Furthermore, transgenic mice lacking specific proteins expressed in the VMH including leptin receptor, steroidogenic factor 1 (SF-1), melanocortin-4 receptor (MC4R), and brain-derived neurotrophic factor (BDNF), exhibits obesity, hyperphagia, and low locomotor activity similar to AC3−/− mice." (PMID 19750222, 2009). "However, since the VMH of germline SF-1 KO mice had disrupted cytoarchitecture, the obesity phenotype in the transplanted animals could be a consequence of impaired VMH formation rather than SF-1 absence in the nucleus." (PMID 23675313, 2013). "Interestingly, selective elimination of LEPRb in the steroid factor 1 (SF1)-expressing neurons of the VMH also produced an obesity phenotype, with a cumulative effect in mice lacking LEPRb in both SF1 and POMC neurons, indicating that these may represent distinct parallel pathways." (PMID 23543912, 2013).
adenoma (22 papers, 2013 to 2025). A neoplasm arising from the epithelium. "Elevated SF1 expression was detected in non‐functional adenomas and Conn's syndrome samples, whereas its expression was nearly absent in PCC tumors." (PMID 40190189, 2025). "CHST7 is a novel pituitary gland specific protein in SF-1 lineage adenomas with a potential role in gonadotroph cell proliferation and lineage differentiation in PA." (PMID 38023219, 2023). "As the Sf1-Rspo1GOF animals aged, the diffuse hyperplasia and cortical thinning gave way to increased frequency of well-circumcised benign nodules and adenomas (6/8 Sf1-Rspo1GOF males and 6/8 Sf1-Rspo1GOF females of 12 months)." (PMID 37102205, 2023). "The RT-PCR and IHC experiments also showed that there were more patients with low CHST7 with SF-1-lineage adenomas and more patients with high CHST7 with a Pit-1 lineage." (PMID 35954244, 2022). "In this study, we found that CHST7 hypermethylation in PAs was associated with the tumor proliferation and cell differentiation of SF-1-lineage adenomas, and CHST7 hypomethylation was related to the cell differentiation of the Pit-1 and T-PIT lineages." (PMID 35954244, 2022). "Further support to the activation of SF-1 in the rat tumors came from the validation of Cyp11b1 and Cyp11b2 overexpression in independent adenoma samples." (PMID 23756599, 2013). "Bioinformatic analysis identified downstream targets of the transcription factor SF-1 as being up-regulated in rat (and human) adenomas." (PMID 23756599, 2013). "Importantly, the null cell adenomas according to the old 2004 WHO classification are now almost entirely assigned to the gonadotroph group (SF-1 positive or GATA3 and ERα)." (PMID 40579705, 2025). "In contrast, our study found uniform expression of SF1 in nuclei of villus, crypts and adenomas." (PMID 33202710, 2020). "However, our study detected SF1 in nuclei of villi and crypts of the intestine and in ApcMin/+ adenomas." (PMID 33202710, 2020). "Recent years have seen an increasing application of the pituitary transcription factors (Pit-1, Tpit and SF-1) to accurately determine the adenoma cells type and distinguish separate primary lesions that are collision tumors or divergent differentiation of a single lesion." (PMID 31598814, 2019). "In another study, 15 SCAs demonstrated greater immunoreactive scores for SSTR2 compared with null cell adenomas (defined in that study as hormone-, SF1-, and PIT1-negative samples; n = 10) and greater immunoreactive scores for SSTR5 compared with SGAs (n = 110)." (PMID 30020466, 2019). "In contrast, several downstream targets of SF-1 were found highly expressed in the adenomas." (PMID 23756599, 2013). "These PIT-1/SF-1 positive sPitNETs differ in several aspects from other acromegaly-associated PitNETs lacking SF-1 expression: they are densely granulated adenomas without GNAS mutations, with ectopic GIPR expression, a distinctive DNA methylation profile, and high level of genomic instability." (PMID 40813692, 2025). "In keeping with the current WHO definition, these adenomas do not show immunoreactivity for any pituitary hormone, nor do they express any of the following transcription factors: Pit-1, SF1, and TPit." (PMID 40002261, 2025). "These adenomas were more often diagnosed at a younger age, microadenomas without tumour expansion and SF‐1 negative/PIT‐1 positive (data not shown)." (PMID 39001600, 2024). "The introduction of steroidogenic factor 1 (SF1; coded by the nuclear receptor subfamily 5 group A, member 1 gene) IHC in the diagnosis of pituitary lesions has shown that many hormone-negative adenomas are, in fact, SGAs." (PMID 30020466, 2019). "Within this category, the preoperative prediction of Ki-67 index was the most common specific endpoint, analyzed in 5 studies, followed by efforts to distinguish subtypes such as SCAs, NCAs, and Tpit/Pit-1/SF-1 families, and to classify functional versus non-functional adenomas." (PMID 41010799, 2025).
adenoma (continued). "Additionally, SF1 is highly expressed in differentiated villous cells, but it is not observed in adenoma or undifferentiated intestinal crypt cells of the intestinal epithelium." (PMID 32811430, 2020). "According to this classification scheme, hormone-negative adenomas may be classified in four groups: SF1-positive gonadotroph adenoma, PIT1-positive adenoma, TPIT-positive corticotroph adenoma, and transcription factor-negative null cell adenoma." (PMID 30176934, 2018).